IGHG3 (immunoglobulin heavy constant gamma 3 (G3m marker))
Description:
Constant region of immunoglobulin (Ig) heavy chains. Igs are membrane-bound or secreted glycoproteins produced by B lymphocytes. In the recognition phase of humoral immunity, the membrane-bound Igs serve as receptors, which upon binding to a specific antigen trigger the clonal expansion and differentiation of B lymphocytes into Ig-secreting plasma cells. Secreted Igs known as antibodies mediate the effector phase of humoral immunity by blocking the interaction of infectious antigens with cellular receptors (via the antigen-binding region) and eliciting effector mechanisms that lead to pathogen neutralization (via the constant region). The antigen-binding region is formed by the variable domain of one heavy chain paired with the variable domain of its associated light chain. Each Ig molecule has two antigen-binding sites with remarkable affinity for a particular antigen due to V-(D)-J rearrangement, somatic hypermutations and affinity maturation of the variable domains upon antigen exposure. The constant region defines the Ig isotype that perform distinct sets of effector functions. B cells diversify and rearrange their Ig constant regions through class-switch recombination, a process by which the constant region is switched from one Ig isotype to another, namely from IgM and IgD to IgG, IgA and IgE. The constant region of Ig gamma-3 (IgG3) isotype interacts (via the fragment crystallizable, Fc) with receptors on innate immune cells and the complement system to mediate humoral effector functions, including antibody-dependent cellular cytotoxicity or phagocytosis, complement-dependent cytotoxicity and inflammatory responses.
Synonyms: IgG3
Gene: Immunoglobulin constant (C) gene on chromosome 14 (105,764,503 to 105,771,405, reverse strand). Ensembl gene ENSG00000211897.
Subcellular location: Secreted (Isoform 1); Cell membrane (Isoform 2)
Homologues: Paralogues in human: IGHG1 (85% identical), IGHG2 (82% identical), IGHG4 (82% identical), IGHE (32% identical), IGHM (29% identical), IGHA1 (26% identical), IGHA2 (25% identical), IGHD (22% identical), IGLL1 (11% identical), IGLL5 (11% identical), IGLC1 (8% identical), IGLC7 (8% identical), and 65 more.